MKI67 (marker of proliferation Ki-67)
Diseases named in the same sentence as MKI67 in open-access papers (continued):
Sharing a sentence is not in itself a finding about the gene and the disease.
tumor (continued). "As expected, MKI67 was weakly expressed in most benign tissues and highly significantly overexpressed in the tumour samples." (PMID 28430799, 2017). "More than 22,000 articles are indexed in PubMed concerning this protein, most of them using MKI67/Ki-67 as a marker, especially for comparing proliferation between tumor samples in the field of cancer research." (PMID 29036270, 2017). "In both the patients, ER, PR and HER2 expression remained homogenous across tumor pieces, while, MKI67 expression varied in spatially separated tumor pieces." (PMID 29187174, 2017). "Similar to previous cohort, MKI67 expression tends to me more heterogeneous across intra-tumor pieces than ER, PR and HER2 expression." (PMID 29187174, 2017). "Immunohistochemical examination of MKI67 (marker of proliferation, Ki67) revealed that MKI67-positive tumor cells were less common in the HSC3-KO tumor compared with the HSC3 tumor." (PMID 27512993, 2016). "PRDM1 can also promote the apoptosis of tumour cells by specifically suppressing MKI67 and proliferating cell nuclear antigen." (PMID 24438193, 2014). "Taken together, the tumor proliferation marker MKI67 and a new prognosis marker GRHL2 collaborate with several mesenchymal markers as a “poor-prognosis” gene-set, while two epithelial markers perform as a “good-prognosis” gene-set." (PMID 23441166, 2013). "The Ki-67 protein, also known as MKI67, exists in actively proliferating cells in the G1, S and G2 phases, and is a proliferation-related nuclear marker of tumor cells." (PMID 24179510, 2013). "The expression of a gene was considered to be correlated with the expression of MKI67 if the pValue <1% with both tumor groups." (PMID 22724020, 2012). "The fraction of MKI67-positive tumor cells (MKI67 labeling index) provides correlation with the clinical course of disease." (PMID 21776270, 2011). "Moreover, primary tumor samples had exclusive mutations in AKAP9, KDM2B, MAGED1, MKI67, PCLO, and TRAF1." (PMID 41614915, 2026). "After identifying the prognosis value of MKI67 expression, we investigated the potential relationship between MKI67 expression and tumor-infiltrating immune cells, an essential component of the Tumor Microenvironment (TME), across various cancer types by xCell algorithm." (PMID 40070823, 2025). "Furthermore, RNA in situ expression of Mki67 and validation with IHC for Ki67 expressed throughout the cell cycle, confirmed active proliferation in tumor nodules of β-M NR animals." (PMID 40442146, 2025). "Moreover, we thoroughly revealed the correlation between MKI67 and tumor-infiltrating immune cells and the related pathways using pan-cancer datasets." (PMID 40070823, 2025). "Our scRNA-seq data for intra-tumoral TCR-T cells revealed the age-related decrease in the frequency of Mki67-expressing Tpex-like cells (cluster 0), which can persist in tumors and sustain effective anti-tumor CD8 T cell responses more effectively than Tex cells." (PMID 39925817, 2025). "Furthermore, the upregulation of PCNA and MKI67 genes, associated with tumor cell proliferation, was observed in the C2 subtype, indicating that patients with short-term survival may exhibit aberrant dysprogression of cell cycles and increased tumor cell proliferation." (PMID 40362506, 2025). "Later, to understand the effect of the C1GalT1 gene expression level on tumor proliferation, the expression levels of the C1GalT1 and MKI67 genes were compared across various cancer types, and the relationship between the C1GalT1 expression levels was analyzed." (PMID 40548474, 2025). "Furthermore, tumor immunostaining showed that EZH2 inhibition reduced cell proliferation (MKI67), increased cell death (cleaved Caspase-3 [CC3]), and restored MHC-I expression in CRPR2 tumors." (PMID 41353272, 2025). "This indicates that the absence of Olig1/2 leads to a downregulation of MKI67 expression, which means the reduced tumor growth is caused by slowed tumor proliferation." (PMID 40428395, 2025).
tumor (continued). "The Ki-67 marker is a protein encoded by the MKI-67 gene, which is located on chromosome 10q26.2; this protein is expressed in all phases of the cell cycle and has been proven to be a biomarker of tumor aggressiveness and a predictor of neoplastic evolution." (PMID 40976132, 2025). "In B16 tumours, the Toxlo population consisted of five main subclusters, including two Mki67+ proliferating Teff cell populations (Prolif1 and Prolif2), two progenitor Tex cell populations (TexProg1, TexProg2), an intermediate exhausted (TexInt) population and a small naive-like cell population." (PMID 41366157, 2025). "In summary, we investigated the expression characteristics, prognostic value, relationship with tumor-infiltrating immune cells, and related pathways of MKI67 in pan-cancer from a multi-group bioinformatics perspective and 10028 patients data in the context of immuno-oncology." (PMID 40070823, 2025). "This suggests that MKI67-positive cells may play crucial roles in tumor growth and progression, particularly in the rapid proliferation and division of tumor cells." (PMID 40666516, 2025). "All five TFs exhibited peak expression in C2 MKI67+ tumor cells." (PMID 40842994, 2025). "Moreover, according to the expression of MKI67 (Ki-67), the Div-cell clusters were isolated from CAFs, OS cells, macrophages, and tumor-infiltrating lymphocytes." (PMID 40296919, 2025). "Proliferating cells (MKI67+) were interspersed throughout the tumour tissue." (PMID 40335697, 2025). "Immunohistochemical staining for marker of proliferation Ki-67 (Ki-67) and H&E staining in tumor slices showed that the most cell death and the least cell proliferation occurred in the X-ray + Mn-ZIF-8 MNs treatment group, further revealing the Mn-ZIF-8 MNs-induced RT enhancement." (PMID 40585994, 2025). "The relative expression levels of these five TFs were elevated in C2 MKI67+ tumor cells." (PMID 40842994, 2025). "This study explored the expression, prognostic value, and tumor-infiltrating immune of MKI67 in the TCGA database by pan-cancer, and then performed immunohistochemical, correlation analysis and prognostic analysis using 10028 patients of the top 10 cancer patients in China we collected." (PMID 40070823, 2025). "To elucidate the spatial relationship between SPP1+ macrophages and proliferating tumor cells (MKI67+), we screened for SPP1+ macrophage‐enriched spots on the ST slide, then calculated the surrounding signals of proliferative tumor cells, and finally determined the correlation between the two." (PMID 39716897, 2024). "In the tumor and peritumoral area of the SH animals, relative to the control animals, there was an increase in Pten, Egf, Egfr, and Pcna expression; the expression of Cmet increased only in the tumors, and Mki67 increased in the peritumoral area." (PMID 39063041, 2024). "We also examined the role of signaling pathways and related ligand-receptors pair in osteoclasts, analyzing interactions between osteoclasts and other cell types using Cellchat methods, particularly focusing on the crosstalk between C2 MKI67+ Osteoclast and tumor cells." (PMID 39936154, 2024). "Quantitative analysis of the sample source demonstrated that Treg cells expressing MKI67 were predominantly located within tumor tissues, accounting for a higher frequency of Tregs in the TME (193/8907, 2.2%) compared to those in the peripheral blood (20/1859, 1.1%)." (PMID 39438442, 2024).
tumor (continued). "Under the stimulation of tumor antigens, high expression of Mki67 on CD8+ T cells can promote their proliferation, further increasing the number of effector cells with anti-tumor effects and has been suggested to be associated with a better prognosis in various solid tumors." (PMID 38280084, 2024). "IHC staining confirmed that the co-treatment showed the most reduced marker of proliferation Ki-67 and enhanced cleaved caspase-3 staining, arguing a more significant inhibition of tumor cell proliferation and intratumoral cell apoptosis in the xenograft tumors." (PMID 39406703, 2024). "However, the pBADSer99/BAD ratio in TNBC specimens was positively correlated with higher tumor grade, a higher degree of lymph node metastasis and higher MKI67 labeling, which are independent predictors of a poor outcome in TNBC26–28." (PMID 38200104, 2024). "In addition, we observed an increase in the expression of cytotoxicity (PRF1, GNLY, GZMB) and proliferation (MKI67) markers in the CD8+ T cells in PI3K/mTORi+PD‐1i‐treated tumours." (PMID 38711203, 2024). "Moreover, several genes from the G2M downregulated gene set, including MKI67, MCM2, CCND1, and their STRING-interacting genes MECOM, TYMS, and MTHFR, are associated with neoplasms." (PMID 37958729, 2023). "Ki67, also known as MKI67, is a proliferation-associated nuclear marker of tumor cells." (PMID 37120543, 2023). "Interestingly, the Ki-67 protein (MKI67)-expressing proliferative cancer cells were located at the tumor margin between LAMC2- and SPRR3-positive cells, further supporting the proliferative potential to differentiate into various mEpC types." (PMID 37853464, 2023). "It is speculated that E2F8 is upregulated in TNBC, which affects the proliferation and development of MKI67+ progenitor cells and tumor cells, as well as the poor prognosis of patients." (PMID 37686305, 2023). "However, tumor-related genes (MKI67, CD34) and CAFs (FAP) were downregulated in the Nb-TriTE group compared with the other groups." (PMID 38031188, 2023). "Thus, we performed RNAscope staining and detected a coexpression pattern of FABP5, NME1, and MKI67 across the tumor tissues." (PMID 37402315, 2023). "It is speculated that the high expression of FOXM1 will affect the proliferation of MKI67+ progenitor cells and tumor cells, resulting in a worse prognosis." (PMID 37686305, 2023). "In addition, tumor proliferation marker MKI67 was also reduced, and the expression of caspase-3 increased in the lncRNA MEG3 group." (PMID 36005145, 2022). "Interestingly, we detected a distinct stromal subcluster with a proliferating phenotype (MKI67), which was enriched in the tumor compartment." (PMID 36180422, 2022). "Moreover, Mki67 levels were about tenfolds increased in Myc-R26Met compared with Alb-R26Met tumours." (PMID 36433941, 2022). "As MKI67 is a protein associated with cell proliferation, these results suggest that TIPE1 expression in DLBCL may contribute to tumor growth." (PMID 36118167, 2022). "MKI67 expression is associated with a higher tumour grade and early disease recurrence, and WDFY4 plays a critical role in the regulation of certain viral and tumour antigens in dendritic cells." (PMID 35653351, 2022). "Indeed, pathological diagnostic results indicated a high level of MGMT expression and high percentage of KI67+ (also known as MKI67+) tumor cells (#p3 60%, #p4 50%) in the two patients with relapse." (PMID 35199829, 2022). "Additionally, an increase in apoptotic marker “caspase 3” and a decrease in tumor marker “MKI67” were detected after the expression of lncRNA MEG3 with or without HCV core protein (C191)." (PMID 36005145, 2022).
tumor (continued). "Our limited data with time between archival and fresh tumor collection indicates the within-patient difference in MKi67+CD8+ levels by tissue type increases with time, but we were unable to identify a clear time threshold for the acceptable collection window for archival tissue." (PMID 35558070, 2022). "Moreover, we used the well-known proliferation marker MKI67 to reflect tumor proliferation across cancer samples." (PMID 35614079, 2022). "Accordingly, the expression of MKI67 correlates with tumour grade in many cancers." (PMID 35865633, 2022). "Additionally, we performed an analysis based on the TCGA database, which showed that the expression of TPX2 positively correlated with that of MKI67 in tumor-infiltrating CD8+ T cells in HCC." (PMID 35273149, 2022). "Finally, immunocytochemistry results detected a significant increase in apoptotic marker caspase-3 and a decrease in tumor marker MKI67." (PMID 36005145, 2022). "At the end of tumor evolution, MKI67, TOP2A, and CDK1 genes began to express." (PMID 34397824, 2021). "Moreover, the expression of MKI67 increased with higher levels of tumor PD-L1 in C01, C11, and C12, while the expression of certain apoptotic genes, such as CASP8 in C01 and C12, and CASP3 in C11, was downregulated." (PMID 33754038, 2021). "Consequently, MKI67 levels were significantly related to tumour purity within 14 cancers and B cell infiltration degrees within 23 cancers." (PMID 34724892, 2021). "MKI67 plays a vital role in the tumour microenvironment (TME) and congenital immunity." (PMID 34724892, 2021). "Hence, tumor heterogeneity should be considered in this case, since there were discrepant MKI67 expression values in different adjacent sections of the same tumor tissue." (PMID 34572945, 2021). "Much attention is currently given to the proliferation-related mechanism of BC due to the functional specificity of BIRC5/survivin in activating Aurora B kinase within the chromosomal passenger complex, and its co-localization with other tumor proliferation genes MKI67, CCNB1, and AURKA." (PMID 34064473, 2021). "Therefore, based on the expression of p27 and MKI67, we found a proliferative enriched tumor and a quiescent enriched tumor in D6 and D19 spheroids, respectively." (PMID 32728097, 2020). "We further assessed the correlation of JPT1 and MKI67 transcript expressions using a public RNA‐seq dataset established from 540 EC patient's tumor tissues, and found that these genes were positively correlated in EC patient tissues (Spearman = 0.37, P < .0001)." (PMID 31808620, 2020). "In order to survey tumor heterogeneity over time, we evaluated the expression of MKI67 and p27." (PMID 32728097, 2020). "Since MKI67 was over-expressed in both TB and LUAD lungs, we speculated that host MKI67 could be an important mediator of tumor cell proliferation and migration that is employed by Mtb during infection." (PMID 33097805, 2020). "It should be pointed out that other than MKI67, there might be additional host genes involved in Mtb-promoted tumor cell proliferation, migration and invasion." (PMID 33097805, 2020). "Furthermore, we found that gene expression of INPP4B, CDK1, and ERBB2 was statistically significantly connected with patient survival in the same manner as the commonly used reference genes ESR1 (for ER status) and MKI67 (for tumor grade or proliferation)." (PMID 31315058, 2019). "Therefore, we mapped proliferation of co-cultivated tumor cells by the expression of MKI67, a proliferation marker, as well as cell confluence of both naive and co-cultured tumor cells in a time dependent manner." (PMID 31561550, 2019). "In the reactive astrocytes from the tumor we identified an increased expression of immune associated genes such as CHI3L1, HLA-DRA, CD274, HLA-DRB3, CD37, as well as genes that contributed to proliferation (MKI67, ANXA2) and complement components (C1S, C1R)." (PMID 31186414, 2019).
tumor (continued). "Second, luminal A CCND1-amplified tumours display gene expression changes consistent with more aggressive tumours, specifically increased MKI67 and decreased PGR gene expression in addition to an overlap in genes differentially expressed in CCND1-amplified luminal B tumours." (PMID 30819233, 2019). "Immunohistochemistry for Ki67 (MKI67), a nuclear antigen which is present in all but the G0 phase of the cell cycle and therefore expressed in proliferating cells, can be used to determine tumor proliferation index." (PMID 29349710, 2018). "Moreover, the expression of mki-67, a proliferation marker, in GC tumor at stage 3–4 was higher than in GC tumor at stage 1–2." (PMID 29921305, 2018). "Although we observed homogeneous mRNA levels across different regions of the same tumor, the corresponding biomarker protein (IHC based) expression (i.e. Ki-67 for MKI67) were more heterogeneous across spatially separated tumors (verified by board certified pathologist L.W)." (PMID 29187174, 2017). "Furthermore, 32% of patients with low tumor TGFβ1 expression have high MKI67 expression, whereas only 7% of patients in the high TGFβ1 expression group have high MKI67 expression (P = 0.009)." (PMID 27895310, 2017). "Along these lines, single-gene MKI67 RT-qPCR may be worth considering as a golden means for assessing tumor proliferation due to its unique ability to combine technical advancements and diagnostic accuracy with more affordable pricing." (PMID 28193205, 2017). "Tumor and non-tumor samples differed significantly in the expression of 10/22 genes: CCNB1, CLDN4, CLDN6, MMP2, MUC1 (all: p < 0.05), BAG1, SERPINB3 (all: p < 0.01), CD44 (standard variant), MKI67, and MYBL2 (all: p < 0.001)." (PMID 27542596, 2016). "Finally, immunodetection of Ki-67/MKI67 (cellular proliferation marker) decreased in the tumours of mice treated with MRS1220 (50% less) and MRS1220-Vc (53% less), but not in the group treated with vincristine alone (1.42 fold)." (PMID 27634913, 2016). "MKI67 results were obtained for 18 primary and six recurrent tumours in the CNS PNET cohort." (PMID 19293793, 2009). "MKI67 is an important prognostic gene in HCC, showing high expression in HBV/HCV-associated cases and being incorporated into hypoxia-related prognostic models, indicating its involvement in virus-induced tumor progression and hypoxia-driven cellular proliferation." (PMID 41153430, 2025). "Additionally, the expression of MKI67/Ki-67 was evaluated in the tumor tissues." (PMID 39477683, 2025). "The ‘tumor cells 1’ cluster had the gene expression characteristic of stem-like tumor cells with an elevated expression of genes involved in cell division and chromosome segregation such as Top2a, Mki67, Cenpf, Cenpe, Incenp, Anln, Ccna2, Kif20b, Ccnb1, and Smc4." (PMID 39769061, 2024). "Further cell cycle analysis of cancer cells showed that zebularine inhibited tumor cell growth, mainly by suppressing cell cycle G1 phase and expression of cell proliferation-related genes Pcna; however, we did not see the consistent change in the mRNA expression of Mcm6 and Mki67 by zebularine." (PMID 38755254, 2024). "Also, the mRNA levels of CEACAM1 and CEACAM6 (known membrane markers of malignant epithelial cells in various adenocarcinoma, including colon cancer), as well as MKI67 (a proliferation marker), were significantly higher at tumor center and tumor invasive margin than adjacent normal in PanCK(+) AOIs." (PMID 37964075, 2023). "Gene expression analysis showed that chemokines such as Ccl2 and Ccl8 and cell proliferation markers such as Mki67 and Birc5 were highly expressed in cluster 3, indicating that 8 mg/kg of smTRAIL may induce tumor cell “activation” and secretion of chemokines to recruit immune cells." (PMID 37605148, 2023).